KAT6B (lysine acetyltransferase 6B)
Diseases named in the same sentence as KAT6B in open-access papers (continued):
Sharing a sentence is not in itself a finding about the gene and the disease.
Alzheimer disease (1 paper, 2024). A progressive, neurodegenerative disease characterized by loss of function and death of nerve cells in several areas of the brain leading to loss of cognitive function such as memory and language. "As KAT6B has been implicated in mitochondrial function in Alzheimer’s disease and aspects of the KAT6B-related KAT6A syndrome have been proposed to arise from mitochondrial dysfunction, we assessed mitochondrial morphology and function across SBBYSS HEK293T cell lines." (PMID 38557491, 2024).
anaemia (1 paper, 2025). "Recipients of Kat6a–/–Kat6b+/+ foetal liver cells reached the ethical endpoint within 21 days (p < 10–6), exhibiting anaemia (p = 10–6) and minimal contribution of the foetal liver donor cells to the recipient peripheral blood." (PMID 40000651, 2025).
Anxiety (1 paper, 2024). Intense feelings of nervousness, tension, or panic often arise in response to interpersonal stresses. "As GPS has been proposed to result from gain-of-function mutations in KAT6B, reduced anxiety levels in a loss-of-function mouse model could be relevant." (PMID 38557491, 2024). "This suggests that VPA treatment led to a partial restoration of normal anxiety behavior in Kat6b+/– mice in this test." (PMID 38557491, 2024). "As adult Kat6b+/– mice demonstrated reduced anxiety in the open field and elevated O maze, maternal separation may not have been sufficiently stressful to induce vocalizations in Kat6b+/– pups." (PMID 38557491, 2024). "Kat6b+/– mice spend more time in the open, suggesting decreased anxiety." (PMID 38557491, 2024). "The lack of appropriate anxiety observed in ALCAR-treated Kat6b+/+ and Kat6b+/– mice is consistent with observed anxiolytic effects of ALCAR in rodents." (PMID 38557491, 2024). "The lack of appropriate anxiety in Kat6b+/– mice is not a commonly described trait in individuals with SBBYSS; however, some individuals with GPS present with increased anxiety and aggression." (PMID 38557491, 2024).
autism (1 paper, 2024). Persistent deficits in social interaction and communication and interaction as well as a markedly restricted repertoire of activity and interest as well as repetitive patterns of behavior. "In this study, we showed that Kat6b+/– mice display behavioral anomalies resembling certain aspects of the human KAT6B deficiency syndrome, SBBYSS, including learning difficulties and autism-like presentation." (PMID 38557491, 2024). "Finally, the sociability and social-recognition deficits in Kat6b+/– mice mirror autism-like traits observed in some individuals with KAT6B disorders, including limited social interactions, impaired communication, restricted interests, and difficulty in sensory processing." (PMID 38557491, 2024).
autism spectrum disorder (1 paper, 2024). A spectrum of developmental disorders that includes autism, and Asperger syndrome. "Our finding that ALCAR treatment improved learning and memory in Kat6b+/– mice is congruent with ALCAR treatment of individuals with autism-spectrum disorders improving cognition." (PMID 38557491, 2024).
CHARGE syndrome (1 paper, 2021). CHARGE syndrome is a multiple congenital anomaly syndrome characterized by the variable combination of multiple anomalies, mainly Coloboma; Choanal atresia/stenosis; Cranial nerve dysfunction; Characteristic ear anomalies (known as the major 4 C's). "This study confirms CS as a feature of CHARGE syndrome, Floating–Harbor syndrome, KAT6B-related disorders, and suggests CS as a feature in Kleefstra syndrome and 2q37 deletion syndrome." (PMID 33288889, 2021).
endometrial stromal tumor (1 paper, 2024). Neoplasms of the endometrial stroma that sometimes involve the myometrium. "In these scenarios, molecular testing should ideally cover not only the KAT6B/A::KANSL1 fusion but also other relevant fusions associated with endometrial stromal tumors." (PMID 39392508, 2024).
Failure to thrive (1 paper, 2025). Failure to thrive (FTT) refers to a child whose physical growth is substantially below the norm. "Similarly, KAT6B deficiency or KAT6B harboring loss of function (LoF) mutations resulted in defects in the development of central nervous system, and failure to thrive in the postnatal period." (PMID 41357671, 2025).
heart abnormalities (1 paper, 2022). "Ventricular septal defects and other congenital heart abnormalities are present in more than 50% of individuals with inactivating mutations in the KAT6A or KAT6B genes." (PMID 36386811, 2022). "KAT6A homozygous deletion mice (KAT6A−/− mice) have ventricular septal defects, and more than 50% of individuals with inactivating mutations in KAT6A or its paralog KAT6B present with ventricular septal defects and other congenital heart abnormalities." (PMID 36386811, 2022).
hypothyroidism (1 paper, 2025). Abnormally low levels of thyroid hormone. "The heterozygous variants of the KAT6B gene are related to KAT6B disorders with a highly variable expressivity, in which functional or structural thyroid abnormalities such as hypothyroidism and thyroid agenesis or hypoplasia are present in many affected individuals." (PMID 40391015, 2025).
lymphoma (1 paper, 2020). A malignant (clonal) proliferation of B- lymphocytes or T- lymphocytes which involves the lymph nodes, bone marrow and/or extranodal sites. "In contrast, CBP, KAT inhibitors discovered recently, and A485, p300 inhibitor, showed antiproliferative effects on lineage-specific tumor cell lines; however, KAT6A and KAT6B inhibitors induced cell senescence and inhibited mouse lymphoma growth." (PMID 32399051, 2020).
metastatic tumour (1 paper, 2023). "Driver gene aberrations occurring exclusively in CSF cfDNA and not shared with primary/metastatic tumour or plasma cfDNA (where sequenced) were found in genes involved in histone modification (KAT6B, KMT2D, NUTM2A) and microtubule formation (PDE4DIP)." (PMID 37973922, 2023).
prostate carcinoma (1 paper, 2022). A carcinoma that arises from epithelial cells of the prostate gland. "What’s more, KAT5 and KAT6B positively regulated prostate cancer cell proliferation through phosphatidylinositol 3-kinase (PI3K)/protein kinase B (Akt) signaling pathway, which was aberrantly activated in hepatocellular carcinoma." (PMID 35383533, 2022). "Moreover, one study also demonstrated that KAT5 or KAT6B knockdown could suppress the AKT/AKT signaling in prostate cancer cells." (PMID 35383533, 2022).
smooth muscle neoplasms (1 paper, 2024). "Given the incomplete current understanding of these neoplasms, we suggest that all uterine mesenchymal neoplasms with overlapping morphology and immunophenotype between endometrial stromal and smooth muscle neoplasms undergo molecular testing to identify a KAT6B/A::KANSL1 fusion." (PMID 39392508, 2024). "Uterine mesenchymal tumours harboring KAT6B/A::KANSL1 gene fusions typically exhibit histological and immunophenotypic overlap with endometrial stromal and smooth muscle tumours." (PMID 39392508, 2024). "Furthermore, besides KAT6B/A::KANSL1 gene fusions, RNA sequencing did not identify prototypical gene fusions typically seen in HGESS or smooth muscle tumors in any of the outlier tumours." (PMID 39392508, 2024).
venereal disease (1 paper, 2025). "Including healthy controls with no history of tobacco or alcohol use, penile lesions, or venereal disease allowed for the identification of shared mutations (PABPC1, MUC16, and KAT6B) between groups." (PMID 40486961, 2025).
cancer (35 papers, 2009 to 2025). A tumor composed of atypical neoplastic, often pleomorphic cells that invade other tissues. "Conversely, transfection of KAT6B expression vectors into cancer cells with a homozygous KAT6B deficiency led to a reduction in tumor proliferation and a decrease in tumor size." (PMID 41357671, 2025). "In summary, the BRPF1-KAT6A/KAT6B complex with multiple chromatin modules is closely linked with neurodevelopmental disorders and cancers." (PMID 36077605, 2022). "The result showed KAT6B|RELN pair was an independent risk factor in five cancers (CESC, SARC, LIHC, LUAD, and PRAD)." (PMID 36139377, 2022). "In this paper, we depict the molecular structures and biological functions of the BRPF1-KAT6A/KAT6B complex, summarize the variants of the complex related to neurodevelopmental disorders and cancers and discuss future research directions and therapeutic potentials." (PMID 36077605, 2022). "To conclude, aberrations of KAT6A and KAT6B are correlated with cancers, distinct neurodevelopmental syndromes, together with other developmental diseases like craniofacial dysmorphism and skeletal abnormalities." (PMID 41357671, 2025). "Aberrant expression of KAT6A and KAT6B in different types of cancer can be attributed to various prototypes of genetic alterations, including fusion, mutation, amplification, and deletion." (PMID 41357671, 2025). "To conclude, both KAT6A and KAT6B have a crucial impact on the tumor proliferation, metastasis, and drug resistance of multiple types of cancers, via regulating the PI3K/AKT signaling axis, the ER signaling pathway, and cell cycle‐related pathways." (PMID 41357671, 2025). "The dysregulation of KAT6A or KAT6B has been shown to exert a pivotal influence on survival outcomes of a multitude of cancer types, further substantiating their involvement in oncogenesis." (PMID 41357671, 2025). "These 17 translocations were further analyzed in 1,059 mutation-negative NSCLCs, which resulted in the identification of two additional tumors with ADK::KAT6B rearrangement and one carcinoma carrying RPS6KB1::VMP1 fusion." (PMID 40661875, 2025). "These efforts led to the identification of two additional tumors with ADK::KAT6B rearrangement and one carcinoma carrying RPS6KB1::VMP1 fusion." (PMID 40661875, 2025). "In summary, the findings from this phase 1 study establish KAT6A and KAT6B as druggable cancer targets and provide clinical proof of concept in treating HR+/HER2− mBC." (PMID 38824244, 2024). "KAT6B is a major histone acetyltransferase, widely reported during the progression of various diseases, including cancer, cardiovascular diseases, and neurodegenerative diseases." (PMID 35432536, 2022). "Recent pan-cancer analysis of CNV has identified KAT6A and KAT6B as top targets for amplification in different cancers." (PMID 36077605, 2022). "Primary cancer cells classified in C1 shared SNV clusters 18 and 15, including nonsynonymous mutations in transcription activator genes such as ELK4, KAT6B, and MAML3." (PMID 34507604, 2021). "Importantly, the frequent molecular dysregulation of KAT6A and KAT6B correlates with survival outcomes of cancers, contributing to the exploration of a wide array of small‐molecule inhibitors against KAT6 catalytic activity." (PMID 41357671, 2025). "Thesefindings indicate that targeting KAT6A and KAT6B may provide therapeuticbenefits in cancer treatment." (PMID 39958699, 2024). "Previous studies have presented the roles of KAT6B in cancer development." (PMID 35432536, 2022). "Previous studies have identified the function of KAT6B in cancer development." (PMID 35432536, 2022).
cancer (continued). "In addition, KAT6B‐KANSL1 translocations have been identified in a woman with retroperitoneal leiomyoma 99, but how the KAT6B‐KANSL1 translocation drives this cancer remains to be identified." (PMID 31267707, 2019). "In the unclassified subgroup, apart from previously reported mutations in epigenetic regulators in multiple cancers, including KMT2C, KMT2D, KMT2B, PRDM2, NCOR2, KAT6B, and EP300, in this cohort, we also found new recurrent mutations in epigenetic regulators, including CREBBP and PRDM16." (PMID 30950204, 2019). "The MYST family of KATs is primarily localized in the nucleus; however, some studies suggestthat KAT6A, KAT6B, and Tip60 can also locate or translocate into thecytoplasm, as evidenced by immunofluorescence staining and subcellularfractionation analyses in certain cancer cells." (PMID 39958699, 2024). "Moreover, compared with primary cancer tissues, recurrent tissues showed higher p65 nuclear translocation and KAT6B protein levels but lower IκBα protein levels, suggesting more activation of KAT6B/NF‐κB signalling in recurrent tissues." (PMID 36639835, 2023). "The frequency of somatic mutations in KAT6A and KAT6B is reported to be relatively high in cancer, with 2.7% in KAT6A and 2.3% in KAT6B, respectively." (PMID 41357671, 2025). "In cancer, inhibition of KAT6A and KAT6B using smallmolecule compounds WM-8014 and WM-1119 induces cell cycle exit and cellularsenescence in an INK4A/ARF-dependent manner." (PMID 39958699, 2024). "KAT6B-ADK (n = 6), BPTF-PITPNC1 (n = 5), and NCOA3-EYA2 (n = 5) were the most frequent fusions among the common cancer types examined in our study." (PMID 30760718, 2019). "The mRNA expression of histone acetyltransferases in claudin-low cancers displayed no significant up-regulations or down-regulations (mean z-scores of expression between −0.5 and 0.5) except for KAT6B, which was moderately suppressed with a mean z-score of expression of 0.76." (PMID 37504297, 2023).
tumor (19 papers, 2015 to 2025). "These KAT6 inhibitors were shown to exhibit effective inhibition against both KAT6A and KAT6B, induce cellular senescence, and impede tumor growth in models of MYC‐driven lymphoma and AML." (PMID 41357671, 2025). "In Du145 prostate cancer cells, KAT6B upregulation was detected to promote tumor growth through an RNAi screening involving 44 genes involved in histone modifications." (PMID 41357671, 2025). "For instance, a study found that patients with high levels of KAT6B expression in TSCC tumor tissue obtained worse drug response and poorer disease‐free survival, indicating the oncogenic role of KAT6B in TSCC." (PMID 41357671, 2025). "Unsupervised hierarchical clustering and t-SNE analysis of DNA methylation data (Illumina EPIC array) identified a distinct cluster for 8/13 KAT6B/A::KANSL1 tumours (herein referred to as core cluster)." (PMID 39392508, 2024). "Our study cohort consisted of 16 tumours harboring a KAT6B/A::KANSL1 gene fusion (KAT6B::KANSL1, n = 15; KAT6A::KANSL1, n = 1)." (PMID 39392508, 2024). "Genome wide DNA methylation analysis of the study cohort identified a distinct cluster of tumours harbouring a KAT6B::KANSL1 gene fusion (“core KAT6B/A::KANSL1 cluster”), including 8 of 13 tumours analysed herein." (PMID 39392508, 2024). "Twenty-eight tumours harbouring a KAT6B/A::KANSL1 gene fusion have been reported previously, and with the addition of cases we report in the current study, the total is 33 (11 of the cases we report have also been previously documented)." (PMID 39392508, 2024). "The median GI for the core KAT6B/A::KANSL1 cluster tumours was 17 (mean GI 51.7, range 3—266), in stark contrast to DNA methylation outlier tumours which showed a median GI of 272 (mean GI 906, range 8—3796)." (PMID 39392508, 2024). "These experimental results indicate that KAT6B‐dependent NF‐κB signalling activation is responsible for tumour cell repopulation by dying cells." (PMID 36639835, 2023). "Mutual inhibition between lncRNAs (XLOC_003973 and XLOC_010383) and miR‐22, as NF‐κB targets, led to upregulated KAT6B expression and subsequent feedback amplification of the NF‐κB signal, finally resulting in tumour cell repopulation." (PMID 36639835, 2023). "Inhibition of the HAT activity of KAT6B effectively induced tumour cell senescence and arrested tumour growth." (PMID 36639835, 2023). "This environment stimulates growth by activating lysine acetyltransferase 6B (KAT6B)‐dependent nuclear factor‐kappa B (NF‐κB) signalling in living tumour cells." (PMID 36639835, 2023). "Then, we examined the biological effect of KAT6B and found that KAT6B knockdown disrupted the promotive effect on tumour cell repopulation of living cells stimulated by dying feeder cells in vitro and in vivo." (PMID 36639835, 2023). "Importantly, abnormal regulation of KAT6A and KAT6B has been shown to serve as tumor drivers or suppressors, which places a critical impact on the formation, progression, and drug resistance of cancerous disorders." (PMID 41357671, 2025). "Moreover, preclinical data from cell lines and animal models indicate that approaches targeting subunits of KAT6A and KAT6B can effectively inhibit tumor growth via mechanisms including cell cycle arrest and cell senescence." (PMID 41357671, 2025). "However, distinct differences in signaling pathways were noted between KAT6B::KANSL1 tumours and ESN/LGESS." (PMID 39392508, 2024). "Interestingly, 5 tumours harboring a KAT6B/A::KANSL1 gene fusion, hereafter referred to as “outliers”, did not cluster with the core cluster." (PMID 39392508, 2024). "The effect of NF‐κB signalling on tumour cell repopulation was dependent on the KAT6B protein." (PMID 36639835, 2023).
tumor (continued). "High tumour expression of RBP1, or KAT6B is associated with improved patient survival outcomes." (PMID 36147741, 2022). "RT-PCR with all four primer combinations, MORF-1234F/KANSL1–2969R1, MORF-1234F/ KANSL1–2900R1, MORF-1261F/KANSL1–2969R1, and MORF-1261F/KANSL1–2900R1, amplified cDNA fragments strongly suggesting the presence of a KAT6B-KANSL1 fusion transcript in the examined tumor (lanes 1–4)." (PMID 25621995, 2015). "Inhibition of KAT6A and KAT6B could induce senescence and arrest tumor growth." (PMID 37365518, 2023). "In other types of tumors, KAT6A and KAT6B have been reported to mediate tumor proliferation and malignant progression through the PI3K/AKT signaling pathway, while inhibition of KAT6A and KAT6B results in decreased phosphorylation of PI3K and AKT." (PMID 41357671, 2025). "KAT6B::ADK also ranked among the top fusion events according to read count in the FUSCC-LU175 and FUSCC-LU260 tumor samples." (PMID 41213951, 2025). "Analysis of DNA methylation cluster assignments in relation to histological features revealed that while tumours in the core KAT6B/A::KANSL1 cluster were histologically bland, outlier tumours frequently exhibited “high-grade” morphological features." (PMID 39392508, 2024). "The first series included 11 KAT6B::KANSL1 and 2 KAT6A::KANSL1 tumours." (PMID 39392508, 2024). "To further validate this finding, we treated tumor-bearing mice with ectopic expression of KAT6B::ADK and ADK with tamoxifen in vivo, and tumors overexpressing KAT6B::ADK showed a minimal response to tamoxifen treatment, in contrast to the significant tumor inhibition in the control group." (PMID 41213951, 2025). "CNV analysis did not identify significant alterations in the core KAT6B/A::KANSL1 cluster tumours." (PMID 39392508, 2024). "Densitometry analysis showed that KAT6A, KAT6B and KAT7 significantly decreased in KIRC tumor tissues, but KAT5 in KIRC tumor tissues decreased to some extent, but the change was not significant." (PMID 37365518, 2023).